IDO1 (indoleamine 2,3-dioxygenase 1)
Diseases named in the same sentence as IDO1 in open-access papers (continued):
Sharing a sentence is not in itself a finding about the gene and the disease.
tumor (continued). "Being able to induce IDO1-mediated immunosuppressive events and tumour dormancy, IFNs are considered as a key upstream player of IDO1 for switching TRCs into the dormancy state." (PMID 34539663, 2021). "Various studies have demonstrated the importance of KYN-AhR activation in IDO1- or TDO2-expressing tumour cells and its role in enhancing cancer cell survival and motility." (PMID 34680327, 2021). "In the context of TME, both tumor and immune cells, including stromal cells, lymphocytic cells, and dendritic cells, express IDO1." (PMID 34453261, 2021). "Conversely, IFN-I signaling in tumor cells has been shown to upregulate indoleamine-2,3-dioxygenase 1 (IDO1) after radiation, which contributed to radiation resistance and inhibition of immune responses in tumors." (PMID 34925363, 2021). "Meanwhile, IDO1 inhibitors combined with other therapies should be considered as an effective strategy in tumor immunotherapy, such as effectively suppressing tumor growth by synergizing photothermal therapy (PTT), radiotherapy, or chemotherapy." (PMID 35003126, 2021). "There are differences in IDO1 expression and activity between cells derived from different types of cancer, moreover, overexpression of IDO1 in some cancer tissues depends on tumour invasiveness and progression." (PMID 33541164, 2021). "Notebly, IDO1, the markers of tumor-promoting immune cells cDC3-LAMP3, was upregulated in the MIT-high group." (PMID 35087839, 2021). "Under low serine conditions, tryptophan can act as an alternative one-carbon source to support proliferation, and that its combination with dietary serine and glycine restriction can increase the anti-tumor efficacy of the IDO1 inhibitor epacadostat." (PMID 33831358, 2021). "Indoleamine 2,3-dioxygenase 1 (IDO1) is at the apex of the kynurenine pathway and both IDO1 itself and kynurenine have been linked to tumor immunosuppression." (PMID 34771550, 2021). "For example, doxorubicin (DOX) combined with the indoleamine 2,3-dioxygenase (IDO-1) inhibitor indoximod (IND) exhibited a synergistic antitumor response that was superior to a DOX-only treatment in 4T1 orthotopic tumor-bearing mice." (PMID 33918635, 2021). "Meanwhile, upregulation of IDO1 was observed in a series of tumor types in response to the infiltration reaction." (PMID 34657635, 2021). "This knowledge suggests that, at least in part, TDO2 or IDO2 exert a tumor-promoting role through different mechanisms than those described in IDO1 activity." (PMID 34071442, 2021). "Previous clinical studies have suggested the IDO1 inhibitors, such as 1-methyl-tryptophan, exhibited remarkable tumor suppressive effects in patients with solid tumors." (PMID 34657635, 2021). "In the tumor region and the region close to tumors, we observed that multiple IDO-1+ microglia/macrophages also closely surrounded blood vessels and appeared in the vascular walls or lumen." (PMID 34735466, 2021). "This heightened inflammatory condition further increases IDO1 activity driving a vicious cycle of tumor escape, proliferation, and metastasis." (PMID 33916690, 2021). "Several compounds targeting IDO-1 catalytic activity have demonstrated anti-tumour effects in different preclinical settings." (PMID 34685679, 2021). "Together, evidence indicates that increased IDO1 activity and Trp depletion promotes immunosuppression in the tumor microenvironment, making IDO1 a promising target for therapy in combination with traditional chemotherapeutics." (PMID 33916690, 2021). "First, there is an uncertainty of an exact correlation between IDO1 expression and tumor progression or patients’ outcome." (PMID 33557876, 2021). "Analysis of iNOS and IDO1 expression revealed only a very few iNOS-positive and IDO1-positive TAMs, however, their expression was frequently found in tumor cells." (PMID 33466316, 2021). "IDO1 also suppresses anti-tumor responses through the generation of L-kynurenine, an endogenous agonist of the arylhydrocarbon receptor (AhR)." (PMID 33747948, 2021).
tumor (continued). "Expression of PD-1, B7-H4, and IDO1 was heterogeneous in the different tumor types with LMS tumors presenting a higher B7-H4 expression than ESS and UUS." (PMID 34799669, 2021). "Ideally, these measurements should be tested in tumor tissues, which can provide intuitive evidence of IDO1 inhibition." (PMID 33557876, 2021). "Emerging evidence indicates that IDO1 is highly expressed in various human malignancies and is important for regulating cancer progression and tumor immune microenvironment." (PMID 34631703, 2021). "IDO1 is an enzyme produced from various cell types, such as a small subset of plasmacytoid DCs in mouse tumor-draining lymph nodes, and it leads to tumor escape via the suppression of T cell activation in the TME." (PMID 34572263, 2021). "Comparison of transcriptional expression of IDO1 between tumor and normal tissues revealed significant elevation of IDO1 (p < 0.001) in tumor samples." (PMID 34769098, 2021). "One mechanism of tumour immune evasion involves the induction of indolamine‐2,3‐dioxigenase‐1 (IDO‐1) by IFN‐γ." (PMID 34310018, 2021). "IDO1 inhibition has, therefore, been proposed as a potential strategy to break dormancy, promote tumour suppression, and simultaneously improve other anti-cancer treatments, including chemotherapy." (PMID 34539663, 2021). "Tryptophan substituted for serine as a one-carbon donor, with serine restriction improving the anti-tumor activity of IDO1 inhibitor epacadostat." (PMID 33831358, 2021). "As labeling was higher in KPC-IDO1 tumors, it strongly suggests that labeling primarily occurs via tumor-specific IDO1 expression." (PMID 33831358, 2021). "They combined PEG-PS with NLG919, a prodrug of IDO-1 inhibitors, to synthesize a prodrug vesicle that specifically accumulated at the tumor site." (PMID 34158855, 2021). "Since IDO1 is the principal enzyme of the KP in normal and tumor tissues, we studied its expression in SK-Mel-28 in response to dex." (PMID 33806305, 2021). "The contribution of IDO1-induced KYN generation by tumor cells on PD-1 expression was evaluated using anti-CD3/anti-CD28 activated CD8+ lymphocytes." (PMID 34025677, 2021). "1-MT, an IDO1 inhibitor, added with two-fraction radiotherapy significantly reduced tumor size and increased survival in bears with GBM compared to untreated controls." (PMID 34659216, 2021). "Preclinical and preliminary clinical data demonstrate evidence to anti-tumor activity of IDO1 inhibitors." (PMID 33557876, 2021). "Here, the mechanisms reported in the literatures are summarized about IDO1 in the establishment of tumor immune escape." (PMID 35003126, 2021). "In BLCA, miR-153 anti-tumor activity was mediated by targeting IDO1, further inactivating IL6/STAT3/VEGF signaling pathway." (PMID 33672684, 2021). "Apparently, the PGE2 signalling serves a crucial role in balancing apoptosis and growth in tumours, at least partly, through IDO1 mediation." (PMID 34539663, 2021). "TAM-s, which secrete anti-inflammatory and immune suppressive cytokines (e.g., TGFβ and IL10), enhance the expansion of immune suppressive CD4+ Treg cells, inhibit the functions of CD8+ cytotoxic T and NK cells and similarly to tumor cells also express IDO1." (PMID 35366268, 2021). "We observed that FAM83A was overexpressed in tumor tissues relative to adjacent non-tumor tissues, and the expression of IDO1 showed the opposite relationship (p < 0.001)." (PMID 33959500, 2021). "COX-2 and its downstream effector Prostaglandin E2 (PGE2) are now considered as potential contributors to cancer development and IDO1-dependent tumour dormancy." (PMID 34539663, 2021). "CD8+ T-cell infiltration level can not only be regulated by IDO1 expression levels but also by other biological mechanisms in tumor microenvironment." (PMID 34778035, 2021). "The immunohistochemical analysis included the evaluation of either IDO1 or PD-L1 protein expressed by tumor cells in surgical specimens." (PMID 33922388, 2021).
tumor (continued). "Earlier preclinical studies have reported that single-dose or combined treatment with the IDO1 inhibitor, 1-methyl-tryptophan, induces a significant reduction in tumor cell proliferation." (PMID 34769098, 2021). "For example, the removal of Treg can reduce the tumor burden of mouse models 204, inhibit indoleamine 2,3-dioxygenase-1 activity and enhance the tumor-specific T cell response, reduce the conversion to Treg-like cells." (PMID 33897888, 2021). "The refined six gene tumor immune signature (IDO1, CXCL10, CXCL9, HLA-DRA, STAT1, IFNG) was carried on a sample of cases representative of the Sema4D HIS subtypes using basic nSolver analysis." (PMID 33776991, 2021). "Ido1 deficiency in mice with lung cancer was associated with impaired MDSC expansion and immunosuppressive function, and also with reduced tumour growth and metastasis formation." (PMID 34685679, 2021). "In the phase II trial, only tumor-infiltrated immune cells were tested for IDO1 expression, and a histoscore ≥ 5 was used as an arbitrary cutoff for the IDO1-positive status." (PMID 33557876, 2021). "IDO1 expression levels in CESC were negatively correlated with tumor purity and macrophages but positively correlated with CD8+ and CD4+ T cells, neutrophils, and dendritic cells." (PMID 34778035, 2021). "The evaluation of IHC staining revealed that only the PC3 tumor-bearing mice produced PD-L1/IDO-1 following IFN-γ stimulation." (PMID 33692219, 2021). "In TNBC subtypes, IDO1 and PD-L1 were upregulated by interferon-γ-secreting T cells in the tumor microenvironment." (PMID 34381711, 2021). "Dexamethasone can decrease tumor growth by suppressing PD-L1 and IDO1 pathway, which is consistent to the in vitro and ex vivo findings." (PMID 34175886, 2021). "For example, the immune checkpoint protein indoleamine 2,3-dioxygenase 1 (IDO) is overexpressed in many CRC patients and has been linked to tumour mediated immunosuppression and results in a poor prognosis." (PMID 34236075, 2021). "In cancer immunoediting, IDO1 induction in malignant cells and their microenvironment is a key mechanism to modulate anti-tumor immune responses and thus escape immune surveillance." (PMID 33922388, 2021). "On the other hand, pro-inflammatory cytokines released by immune effector cells, such as IFN-γ, IL-6, TNF-α, IL-1 and TGF-β, up-regulated IDO-1 on tumor cells, thus representing an immune escape mechanism." (PMID 33920505, 2021). "The expression of IDO1 seems to decrease tumor infiltration of B cells and to increase the infiltration of regulatory T lymphocytes." (PMID 34322485, 2021). "IDO1 expression/activity has been observed in tumor cells as well as in the tumor-surrounding stroma, which is composed of endothelial cells, immune cells, fibroblasts, and mesenchymal cells." (PMID 33922388, 2021). "Unfortunately, cancer cells that have been exposed to IFNγ also upregulate molecules such as PD-L1 and indoleamine 2,3 dioxygenase 1 (IDO1) that cause T cell exhaustion and allow tumor progression." (PMID 34829860, 2021). "Expression of iNOS was found in 74% of samples, expression of CHID1 was found in 100% of cases, expression of IDO1 was found in 60% of samples, and expression of PD-L1 was found in 96% of samples when a cut-off of 1% of positive tumor cells was used." (PMID 33466316, 2021). "One well described mechanism of tumor evasion is the expression by cancer cells or tolerogenic DCs of tryptophan-degrading enzymes such as indoleamine-pyrrole 2,3-dioxygenase 1 (IDO1)." (PMID 33868263, 2021). "Confocal microscopy of IE9mp1-mIDO1 and IE9mp1-EV tumors also confirmed that tumor-derived IDO1 inversely impacted CD8+ TIL frequency." (PMID 34025677, 2021). "The tumor volume and weight were significantly lower in the IDO1-overexpressing group compared to those noted in the control group." (PMID 33390854, 2021).
tumor (continued). "IDO1 is suggested by some research groups to serve as a favorable prognostic marker with a role in anti-tumor immunity, while other studies suggest that IDO1 is implicated in tumor promotion via immunosuppressive effects." (PMID 34769098, 2021). "The two strongest positive correlates of tumor growth are B7-H3 and IDO-1, both of which are emerging immunotherapy targets for GBM41,42." (PMID 34188042, 2021). "Consistent with the TCGA EOC data, syngeneic wild-type (WT) C57BL/6 mice challenged with IE9mp1-mIDO1 displayed earlier onset of tumor burden and a significant decrease in overall survival compared with tumors that lack IDO1 expression." (PMID 34025677, 2021). "While we focused here on the impact of IDO1 on adaptive immunity, its tumor intrinsic role would need to be clarified in future studies." (PMID 34025677, 2021). "In preclinical experiments, immune reconstitution mediated by TILs slowed tumor growth and extended the survival time; however, this effect disappeared after immune system suppression by PD-L1, IDO-1 and eTreg cells." (PMID 33692219, 2021). "In the phase III trial, IDO1 positivity was defined as expression in more than 1 % of tumor or intra-tumoral immune cells." (PMID 33557876, 2021). "The main immunosuppressive mechanism for influencing a tumor for IDO1 is a decrease in tumor infiltration by cytotoxic T cells and an increase in the number of regulatory T cells." (PMID 33466316, 2021). "WT mice bearing IE9mp1-mIDO1 tumors exhibited a non-significant decrease in CD8+ TIL frequency at all time points of tumor growth compared to animals whose tumors lack IDO1 expression." (PMID 34025677, 2021). "In contrast, B7H3, IDO-1 and Galectin-9 positivity on tumor cells was only seen in 21.0% (19/92) of cases, although their expression was predominantly positive in the stromal area." (PMID 35145510, 2021). "The IDO1 expression was also up-regulated markedly at both the mRNA and protein levels within the tumor regions of combination therapy patients." (PMID 34778231, 2021). "How can elevation in circulating tryptophan levels overcome IDO1-mediated immunosuppression in the tumour?" (PMID 33708223, 2021). "Our collective findings highlight the significance of IDO1 in HCC pathogenesis from a tumor cell perspective and support the utility of IDO1-targeted treatments as an effective therapeutic option for HCC." (PMID 34769098, 2021). "In vivo, IDO1 overexpression restricted tumor growth in C57 mice and enhanced the induction of phagocytosis in macrophages." (PMID 33390854, 2021). "As the most advanced IDO1 inhibitor, epacadostat was selected as a positive control in several preclinical studies of other IDO1 inhibitors in some animal models and showed similar IDO1 inhibitory activities and variable anti-tumor activities." (PMID 33557876, 2021). "It was also found that IDO1 is activated in some antigen-presenting cells in various tumours by tumour, MSCs and innate immune cells." (PMID 33921181, 2021). "IDO1 was shown to be overexpressed in 35.5% resection samples from HCC patients with significant tumor metastasis and poor prognosis." (PMID 34769098, 2021). "Upregulation of IDO1 either by tumor-infiltrating myeloid cells or by tumor cells themselves have been described in various malignancies and have been associated with a poor prognosis." (PMID 33920868, 2021). "Despite the pro-tumor efficacy of IDO1 in tumor development and therapy, the role of TDO2, an IDO1 isozyme, remained poorly investigated." (PMID 34657635, 2021). "IDO-1 expression in the immune cells of the TME is regulated by different factors secreted by tumor cells (i.e., Wnt5 and sTGFBR3)." (PMID 33920505, 2021). "IDO1 is expressed in several human tumors and immune cells infiltrating the tumor mass and, for this reason, IDO1 catalytic inhibitors have been used as experimental drugs in cancer immunotherapy." (PMID 33968089, 2021).
tumor (continued). "While our short-term in vivo13C-tryptophan experiment did show a change in tumor tryptophan metabolism due to IDO1 expression, a longer-term analysis (e.g., using constant infusion) would be required to more accurately quantify the scale of this effect." (PMID 33831358, 2021). "Previous literature has suggested IDO1 should be connected to immunosuppression and tumour dormancy." (PMID 34539663, 2021). "In contrast, the pharmacological blocking of IDO1 activity in tumor cells restored NK cells’ cytolytic activity and receptors expression." (PMID 34576041, 2021). "On the other hand, some studies identified IDO1-specific CD4+ and CD8+ T cells in both healthy people and cancer patients that are capable of removing IDO1-expressing cells, including IDO1-positive DCs and tumor cells." (PMID 34576041, 2021). "Human lymphocytes reduced the tumor size; however, PD-L1/IDO-1 attacked TILs and attenuated this process under IFN-γ pathway activation in group C (PC3 tumor+T cells+IFN-γ)." (PMID 33692219, 2021). "The results showed that these T cells directly increase IDO1 expression in intracranial DIPG tumor and are thus a promising adjuvant immunotherapy." (PMID 33807733, 2021). "This suggests that the presence of CD8+ T-cell infiltration in tumor is very strongly correlated with IDO-1 expression, strongly correlated with IDO-2 expression, but not so strongly correlated with TDO-2 expression." (PMID 34367262, 2021). "The expression of certain immune checkpoints (such as PDCD1LG2, HAVCR2, CD276, and IDO1) also played an important role in the regulation of immune response by inhibiting the activation of anti-tumor immunocytes and inducing immune escape." (PMID 34490033, 2021). "In vitro and in vivo assessment of miR-153 expression on BLCA induced HUVEC angiogenesis, and showed that miR-153 suppressed IDO1, a rate limiting enzyme in tryptophan metabolism, which plays a role in tumor cell escape." (PMID 33672684, 2021). "The inhibition of Ido1 resulted in a T cell-dependent anti-tumor response in mice and CCL2 was involved in the recruitment of neutrophils, MDSCs, and monocytes into the TME, which was associated to tumorigenesis." (PMID 35126382, 2021). "In vivo, it markedly reduced the tumor growth in subcutaneous xenograft tumor models by down-regulating IDO1 and activating apoptosis and autophagy." (PMID 33718227, 2021). "IDO1 is an enzyme that exists in almost all of the cells and its inhibition influences the metabolism of tryptophan in immune and tumor cells." (PMID 33390854, 2021). "These human data also highlight the potential intra-tumor variability in IDO1 expression, as seen in KPC tumors." (PMID 33831358, 2021). "Subsequently, several studies showed that IDO1 plays an immunosuppressive role favoring the tumor immune escape." (PMID 34453261, 2021). "Analysis of the expression of CHID1, iNOS, IDO1, and PD-L1 in tumor cells was done using immunohistochemistry." (PMID 33466316, 2021). "Syngeneic animal studies showed that treatment of the IDO1 inhibitor 1-methyltryptophan (1-MT) limited the growth of IDO1-overexpressed tumours." (PMID 34680327, 2021). "Among all enrolled 706 patients, IDO1 expression was positive in 451 (90 %) of 502 patients with evaluable tumor specimens, and the IDO1 expression positivity was determined as higher than 1 % of tumor or immune cells expressed IDO1." (PMID 33557876, 2021). "This study illustrated that IDO1 vaccination effectively induced anti-tumor immune responses in an in vivo model of cancer where the IDO1 expression was exclusively limited to tumor-infiltrating immune cells and not tumor cells." (PMID 33671555, 2021). "Next, IDO1 expression can be regulated by cytokines, such as IL-10 and IFN-γ while IDO1 inhibition can enhance T-cell proliferation and infiltration in the tumor environment and IL-2 production." (PMID 34422661, 2021).